DMWD (DM1 locus, WD repeat containing)
Description:
Regulator of the deubiquitinating USP12/DMWD/WDR48 complex. Functions as a cofactor that promotes USP12 enzymatic activity.
Synonyms: DMR-N9; gene59; D19S593E; DMRN9
Tractability: Antibody: the Human Protein Atlas places it where antibodies can reach. PROTAC: ubiquitination databases record sites on it; its protein half-life has been measured.
Gene: Protein-coding gene on chromosome 19 (45,782,947 to 45,792,845, reverse strand). Ensembl gene ENSG00000185800.
Subcellular location: Cytoplasm; Nucleus; Perikaryon; Cell projection, dendrite
Subcellular location (Human Protein Atlas): Actin filaments; Plasma membrane
Gene Ontology:
Molecular function: deubiquitinase activator activity; protein binding
Biological process: negative regulation of ubiquitin-dependent protein catabolic process
Cellular component: cytoplasm; nucleus; peptidase complex; dendrite; perikaryon
Genetic constraint (gnomAD): Loss-of-function variants: 19 observed, 42.9 expected, observed/expected ratio (o/e) 0.44, 90% interval 0.31 to 0.65. The synonymous counts are far from expectation, so gnomAD's model fits this gene poorly and the ratio says little. Missense variants: 802 observed, 869.79 expected, observed/expected ratio (o/e) 0.92, 90% interval 0.87 to 0.98. Synonymous variants: 515 observed, 407.38 expected, observed/expected ratio (o/e) 1.26, 90% interval 1.17 to 1.36.
Homologues: Orthologues: chimpanzee DMWD (98% identical), dog DMWD (96% identical), macaque DMWD (95% identical), pig DMWD (95% identical), guinea pig DMWD (93% identical), mouse Dmwd (91% identical), rat Dmwd (90% identical), zebrafish DMWD (59% identical), rabbit DMWD (49% identical), Drosophila melanogaster CG6420 (44% identical), Caenorhabditis elegans wdr-20 (37% identical). Paralogues in human: WDR20 (51% identical).
Diseases named in the same sentence as DMWD in open-access papers:
DMWD is named in the same sentence as 5 diseases in open-access papers, as found by Europe PMC text mining. Sharing a sentence is not in itself a finding about the gene and the disease. The quoted sentences say what the papers report.
myotonic dystrophy (3 papers, 2012 to 2016). An inherited progressive disorder affecting the muscles. "In the skeletal muscle degeneration disorder named myotonic dystrophy, the DMWD levels were found deficient." (PMID 27034888, 2016). "DMWD is a widely expressed protein and was suggested to be involved in some of the neuropathological aspects of myotonic dystrophy (DM1)." (PMID 22558366, 2012). "Together, the link between myotonic dystrophy and AD is notable and may indicate a potential role for DMWD in AD as well." (PMID 27328823, 2016).
cataract (1 paper, 2022). Partial or complete opacity of the crystalline lens of one or both eyes that decreases visual acuity and eventually results in blindness. "Although decreased gene expression at the DM1 locus is not sufficient to explain the complex DM1 phenotype, downregulation of DMPK, SIX5 and DMWD genes by epigenic changes in DM1 could participate in some clinical features such as DM1 cataracts, muscle defects or cardiac conduction defects." (PMID 35408837, 2022). "In DM1, downregulation of these genes by epigenetic changes, such as hypermethylation may participate in some clinical features including cataracts, muscle defects or cardiac conduction abnormalities as observed in DMPK, SIX5 or DMWD knockdown mouse models." (PMID 35408837, 2022).
childhood asthma (1 paper, 2023). "The amino acid sequence of DMWD is similar to that of WD repeat domain 20 (WDR20), which is associated with childhood asthma." (PMID 37875944, 2023).
cancer (1 paper, 2024). A tumor composed of atypical neoplastic, often pleomorphic cells that invade other tissues. "Cytoband Chr19q13 is the human syntenic segment for chr7 in mice and contains both cancer-related and muscle disease-related genes (DMPK, DMWD, SIX5 related to Myotonic Dystrophy Type 1)." (PMID 38341433, 2024).
DMWD also shares sentences with these, for which no sentence is quoted: myotonic dystrophy type 1 (1 paper).